CD68 (CD68 molecule)
Diseases named in the same sentence as CD68 in open-access papers (continued):
Sharing a sentence is not in itself a finding about the gene and the disease.
tumor (continued). "FAM160A1 was expressed in CD68-positive histiocytes rather than the tumor cells, suggesting that variant FAM160A1 contributes to NKTCL pathogenesis by immune dysregulation." (PMID 34440582, 2021). "However, a higher expression level of VISTA was detected in tumor-infiltrating CD68+ macrophages than in CD3+ T and CD19+ B cells." (PMID 33237432, 2021). "In addition, proliferating, cytotoxic T-cells (CD3 + CD8 + KI67 +), PD-L1 + T-cells (CD3 + PD-L1 +) and macrophages (CD68 +) expressing PD-L1 were more prevalent in the tumor-epithelial compartment than in the tumor-stroma compartment." (PMID 33633208, 2021). "However, the AOM/DSS group had several CD68+ cells in the subserosal layer of the non-tumor regions that were suppressed by Probio-M9 administration (arrows)." (PMID 33808480, 2021). "The TME cell population (CD8, CD163 and/or CD68) of the “OSNew” surgical biopsies (n = 17) was analyzed in 287 tumor regions (total of 1260.3 mm2), being morphologically classified into osteolytic (OL, 83.6%, 1118.3 mm2) and osteoid matrix rich (OM, 16.2%, 142.0 mm2) regions." (PMID 33498676, 2021). "Furthermore, in EBV-negative DLBCL, the CD163/CD68 ratio was higher among advanced-staged/high-tumor burden disease." (PMID 34527580, 2021). "TAMs are also broken down into subsets based on polarization to the M1 macrophage-like phenotype (pro-inflammatory/anti-tumor) CD68+ CD80/86+ CD11c+ iNOS+ and the M2 macrophage-like phenotype (pro-tumor) CD163+ CD204+ CD206+ Arg1+, with M2-like TAMs being the most immunosuppressive." (PMID 34136405, 2021). "CD68 was highly expressed in almost every cluster, except for cluster 12, which may be tumor cells misdefined as TAMs according to the gene signature above." (PMID 34434898, 2021). "Both tumor types, were strongly and evenly positive for CD68." (PMID 35366268, 2021). "This suggests that an increase in the number of CD68+ TAMs infiltrating the tumor stroma may reduce the efficacy of bevacizumab combined with chemotherapy in patients with advanced CRC." (PMID 34445193, 2021). "For PFS analysis, residual tumor disease (HR: 1.97, CI: 1.23–3.16, p = 0.005) and the presence of CD68+ CLSs (HR: 2.11, CI: 1.23–3.64, p = 0.007) in model 1 and the presence of CD163+ CLSs (HR: 2.02, CI: 1.17–3.48, p = 0.012) in model 2 were significantly associated with worse PFS." (PMID 34677277, 2021). "CD68+ macrophages that infiltrate the necrotic areas of the INT group may be considered as M2 macrophages which play a role in tumor growth and provide a poor prognosis." (PMID 34164110, 2021). "Similarly, another study proved that in central tumor areas and around vessels in the infiltration zone there were more CD68+ GAMs in slow-growing tumors." (PMID 34071306, 2021). "We applied three different panels to demonstrate the levels of VISTA in tumor-infiltrating CD68+ macrophages, CD3+ T cells, CD19+ B cells, CD4+ T-helper cells, and CD8+ cytotoxic T cells, as well as to explore the association between VISTA expression and PD-1/PD-L1." (PMID 33237432, 2021). "Additionally, CD8+ T cell/CD68+ M densities were evaluated according to tumor center and invasion front." (PMID 33613757, 2021). "Consistently, immunohistochemical results showed that increased CD68-positive macrophages appeared in the tumor site of HFD-fed mice than in that of ND-fed mice, and majority of the macrophages presented a tumor associated M2 phenotype with positive CD206 staining." (PMID 33708630, 2021). "In addition, the amount of CD68+CD163+ macrophages is reduced in tumor biopsies from RG7155-treated Dt-GCT patients, indicating reduced recruitment of TAMs to TME." (PMID 34359674, 2021). "The results from our study showing the formation of a CD68/PD-1 complex may prove to be valuable in the field of MIBC tumor immunity research." (PMID 34079767, 2021). "Tumor PD-L1 in the brain did correlate with CD68+ macrophage content." (PMID 32974852, 2021).
tumor (continued). "We observed fewer tumor foci in Ncf1 mutant mice, irrespective of αβT, γδT, B-cell deficiencies, or of a functional Ncf1 expression in CD68-positive monocytes/macrophages." (PMID 34257370, 2021). "In addition, some published studies show that a large number of both CD68 + cells in the tumor and CD204 + macrophages can also be a favorable prognostic factor." (PMID 33466316, 2021). "In this study, we show that the Ncf1 mutation protected from tumor colonization, irrespective of the CD68-expressing cell status." (PMID 34257370, 2021). "Moreover, the results from immunohistochemistry showed that there was the same immune‐positive signal for NOD2 and CD68, a macrophage marker molecule, in tumour tissues." (PMID 34268854, 2021). "Interestingly, CD68+ macrophages in the peritumoral region of the tumor with CR robustly expressed PD-L1." (PMID 33946835, 2021). "By using DC-SIGN and CD68 to characterize M2-like TAMs, it was shown that they may contribute to tumor progression and poor prognosis." (PMID 34572939, 2021). "We used multispectral imaging to assess cytokeratin (CK), CD68, CD11c, and PD-L1 expression on each cell and phenotyped cells both as PD-L1+ or PD-L1− cells, and as CK+ tumor cells, CD68+ macrophages, CD11c+ dendritic cells, or CK−CD68−CD11c− other stromal cells." (PMID 34433873, 2021). "Additionally, this analysis identified that CD68+ TAMs tend to cluster with tumor cells and away from stromal cells, while CD163+ and CD206+ TAMs tend to cluster with stromal cells and away from tumor cells." (PMID 33882057, 2021). "It has been suggested that TAMs with an M2-like phenotype (markers CD163, CD204, and CD206) have a pro-tumor effect while M1-like TAMs (CD68, CD80, and CD86) may have an anti-tumor effect." (PMID 33882057, 2021). "Also, some studies reported that the survival effects of CD68+ TAMs tested in stroma and tumor islet were opposite." (PMID 34026635, 2021). "We performed multiplexed immunofluorescence method to identify CD11c+ DCs, CD68+ macrophages, and their PD-L1- or PD-L1+ subpopulations in paired tumor biopsies (n = 36) collected at baseline and during the combination treatment (after radiation, 40 Gy) from the phase Ib trial (NCT03671265)." (PMID 35046943, 2021). "We found that PD1 expression was significantly correlated with CD8+ T cell density at the invasion front of the MSI GC (P = 0.031), whereas PDL1 expression was significantly correlated to high CD68+ M density in the tumor center and invasion front of MSS GC (P = 0.001 and 0.014, respectively)." (PMID 33613757, 2021). "It is remarkable that the tumor in our case showed higher CD68 staining." (PMID 34243786, 2021). "In line with previous reports, tumor-infiltrating CD68+ microglia/macrophages could also be detected in human patient samples (n=5; 4.3% to 16.5% of all cells)." (PMID 33707311, 2021). "However, CD68 is a molecular marker of pan-macrophages, which cannot distinguish different phenotypes of macrophages infiltrated in tumor tissues." (PMID 33928349, 2021). "Also, when the number of macrophages was compared according to tumor heterogeneity evaluated by TA, more CD68-, CD163- and CD204-positive macrophages (p = 0.0078, p = 0.0177 and p = 0.0224, respectively) had infiltrated the heterogeneous tumors." (PMID 34244567, 2021). "Pivotal clinical studies confirmed both the promising pre-clinical data and the prognostic relevance of both total and M2 TAM, in which CD68/CD163 double-positive M2 TAM were associated with an increased micro-vessel density and reduced survival, independently of the tumor stage." (PMID 34298810, 2021). "Interestingly, in the hrHPV+ subgroup (N = 43) high infiltration rates of CD68+ and CD163+ cells in the PT Tumor compartment were associated with LN metastasis (p = 0.031 and p = 0.026, respectively)." (PMID 34194435, 2021).
tumor (continued). "The results showed that the proportions of tumor-associated myeloid cells, regardless of staining by CD11b, F4/80, or CD68, were not significantly changed in SHD-RT-treated tumors." (PMID 33669885, 2021). "IDO-positive tumors contained significantly higher amounts of FoxP3+ Tregs (p < 0.0001), IDO+ stromal immune cells (p < 0.0001), and both CD68+ and CD163+ tumor associated macrophages (TAMs) (p-values < 0.0001), compared to IDO-negative tumors (data not shown)." (PMID 34051744, 2021). "Interestingly, CD68 appeared to be the most applicable immune marker to stratify patients by the outcome of chemotherapy in the nodal stage and tumor stage groups." (PMID 33467469, 2021). "This argument is upheld by the effect of CD68+ macrophage infiltration on gene expression within the tumour, in which increased infiltration can impact genes involved in a range of processes, such as cell death and cell cycle, in addition to the role of regulation of inflammation." (PMID 32843682, 2020). "Stromal CD163+ infiltration was significantly associated with the tumor location in the tongue, and stromal and tumoral CD68+ and CD163+-infiltrating TAMs were more abundant in nonsmokers and non-alcohol-drinkers." (PMID 32630659, 2020). "Staining with the KiM1P antibody (recognizes CD68) showed positive cells in all samples of human breast cancer metastases to CNS and accumulation of amoeboid, positively stained cells in the boundary region between tumor and neighboring tissue." (PMID 32194848, 2020). "Fluorescent monocytes in lungs of CD68-EGFP transgenic mice could be visualized within blood vessels in the process of interaction with tumor cells and nanoparticles." (PMID 33195152, 2020). "Thus, in patients with NSCLC, the expression of CD68 in tumor tissue was significantly higher in comparison with normal tissue, and high amount of CD68+ macrophages positively correlated with a higher TNM stage, peritumoral LVD, and LN metastasis." (PMID 33194645, 2020). "Interestingly, Patients with low peripheral CD16−/CD16 + monocytes usually had low tumor CD68/CD206 macrophages and had worse prognosis." (PMID 32385351, 2020). "The combined PT immunoscore (CD8+, CD4+, and CD68) integrated with dNLR may be a promising marker for the development of an integrated Tumor, Node, Metastasis (TNM) immunoscore." (PMID 33072595, 2020). "We were able to detect macrophages by an anti-CD68 antibody in the tumor tissues." (PMID 32244522, 2020). "CD68+ macrophages showed similar frequencies in all the four tumor types." (PMID 32764562, 2020). "Results of our present study did demonstrate that abundant CD8+ and CD68+ cells could represent a histologically low-scored tumor." (PMID 33244312, 2020). "Several studies showed that high levels of CD68+ macrophages in tumor cell islets were associated with a longer survival in non-small-cell lung cancer (NSCLC)." (PMID 33050070, 2020). "Furthermore, a higher Wnt5a+CD68+/CD68+ ratio was observed at the tumor invasive front, where there exists M2-like TAMs infiltration." (PMID 32228612, 2020). "Samples from these patients’ tumours were double stained for CD68 and CD163." (PMID 32075091, 2020). "In specific, infiltration of CD8+T cells may protect against metastatic spread in PTC, and a high infiltration of CD68+ cells (macrophages) in tumor stroma may predict long survival time." (PMID 32045884, 2020). "Indeed, within stage III tumors, higher CD68 infiltration in the intra-tumoral regions is associated with decreased overall survival, and a higher CD80/CD163 ratio at the tumor invasive front correlates with a favorable outcome." (PMID 32962159, 2020). "As was shown, in tumor spheroids isolated from 128 patients (USA cohort) with advanced stage OC, higher amounts of CD68+ macrophages were found in poorly differentiated OC compared with more-differentiated OCs, and their amount correlated with lymphovascular invasion (LVI) and ascite volume." (PMID 33194645, 2020).
tumor (continued). "High M2 ratio (CD163+/CD68+) in the tumor stroma is a potential marker for predicting malignant clinical outcomes in NSCLC patients, and consideration of M2 ratio and VEGF-C expression in combination may enhance the accuracy of prognostic prediction." (PMID 33228719, 2020). "By immunohistochemical analysis, in tumor tissue, the median level of CD68+ cells/HPF was 49 (range, 25–87), the median level of CD163+ cells/HPF was 45 (range, 9–104), the median level of CD206+ cells/HPF was 7 (range, 3–37), and the median level of PU.1+ cells/HPF was 58 (range, 12–115)." (PMID 32884895, 2020). "Of note, among the CD68+ cells, only few were detected in the tumor cores as Tie2+." (PMID 33266255, 2020). "Compared with patients who did not receive chemotherapy, the density of CD3+ T lymphocytes (23.077 ± 14.353 vs. 25.75 ± 15.226, P = 0.565) and CD68+ macrophages (9.685 ± 4.718 vs. 9.852 ± 7.002, P = 0.923) in the tumor tissue of patients receiving neoadjuvant chemotherapy was lower." (PMID 33489884, 2020). "In addition, in our present study, CD68+ cells were significantly higher in PHEOs with normal histological patterns and negatively correlated with tumor size." (PMID 33244312, 2020). "A reduced number of peritumoural CD68+ cells were also seen in ulcerated tumours." (PMID 32843682, 2020). "Immunohistochemically, the tumor cells show variable positivity for D2-40, CD68, CD34, and SMA." (PMID 32316685, 2020). "Phenotyping of CD8-positive cells, followed by CD68-positive cells, was conducted, which facilitated the removal of potential confounding cells that may be PD-L1 positive and located within the tumour epithelial nests." (PMID 33374775, 2020). "In addition, the density of CD68+ macrophages was more abundant in the tumor than in the peri-tumor (P<0.0001)." (PMID 33228682, 2020). "Moreover, infiltration of both CD68+ and CD163+ TAMs was also significantly associated with high tumor expression of PD-L1." (PMID 32630659, 2020). "The amounts of TAMs (CD163+ and CD68+) and tumor HA were determined by immunohistochemistry." (PMID 31720917, 2020). "A higher CD4+ could be expected to be an earlier event in the sequence of immune process, whereas a preponderance of CD68+ could be a late event reflecting the culmination of the immune process and scavenging the dead tumor cells by CD68+ macrophages." (PMID 32596144, 2020). "Furthermore, immunohistochemistry showed many PD-1+CD68− tumor infiltrating cells, which were likely lymphocytes, in this study." (PMID 32131763, 2020). "Meta-analysis of nine studies (eight from Chinese cohorts and one from USA cohort), including 794 patients, revealed that higher M1(iNOS+ or HLA-DR+)/M2(CD163+) ratio, but not just CD68 or CD163 expression in tumor tissues, was associated with a favorable OS." (PMID 33194645, 2020). "Epithelial CD8 [p = 0.027, hazard ratio (HR) = 0.83], stromal CD68 (p = 3 × 10−4, HR = 0.44) and stromal CD45RO (p = 7 × 10−4, HR = 0.76) were positively associated with survival and remained so when averaged across the tumour and stromal compartments." (PMID 32249277, 2020). "For example, CD68+ macrophages could be of both M1 and M2 type with different cytokine profiles and functional impact on tumor progression." (PMID 32290033, 2020). "The authors hypothesized that the enrichment of “inflammatory” CD68+CD16+ macrophages over immunosuppressive CD163+ macrophages could create a more favorable TME for the anti-tumor activity of Ipilimumab." (PMID 32793228, 2020). "Additionally, the PD-L1+ category outnumbered CD68+ macrophages, as PD-L1 expression is expected in immune related, as well as tumour cells." (PMID 31806878, 2020). "Moreover, the authors reported the absence of active immune surveillance in TGCT, suggesting a potential role for CD68 in tumor immunity." (PMID 33104706, 2020). "CD68 is a pan-macrophage marker, which has been related to tumor-suppressor activity." (PMID 33718347, 2020).
tumor (continued). "CD68+ macrophages were localized within the tumor tissue, at its periphery and its surroundings." (PMID 32194848, 2020). "Furthermore, enhanced delivery (TAMRA fluorescence) to macrophages within the tumor was detected by flow cytometry and by immunofluorescence in CD68+ macrophages (respectively)." (PMID 31710308, 2019). "The positive correlation of both pre-and post-treatment CD68 staining with the pre- and post-treatment SUVmax, respectively, suggests that intra-tumor macrophages may contribute significantly to the observed SUVmax on PET imaging in some cases." (PMID 30999901, 2019). "Subsequent detailed analyses of CD68-positive cells were performed only on viable regions of tumor." (PMID 30999901, 2019). "Three macrophage markers were used to detect tumor-associated macrophages: CD68, which is a pan-macrophage marker, CD163, which is considered to stain for tumor-associated macrophages polarized toward an M2 phenotype, and CD80, which is more associated with M1-like macrophages." (PMID 30879106, 2019). "Staining for CD68 and F4/80 revealed numerous TAMs in the neoplastic epithelium and tumor stroma." (PMID 30938231, 2019). "Furthermore, the relevance of these findings was also confirmed in human hepatocellular carcinoma tumor tissue stainings, where CCL2 expression in tumor cells correlated with the tumor-infiltrating CD68+ TAM and lower numbers of antitumorous CD8+ T cells." (PMID 31921102, 2019). "Despite the locoregional heterogeneity, we found a significant positive association of the amounts of CD68‐, CD163‐ and CD206‐positive GAM subpopulations in the vital tumor core with prolonged overall survival of IDH1R132H‐non‐mutant GBM patients performing a median split for each M/M marker." (PMID 30506802, 2019). "In patient samples, a high density of CD68+ macrophages in the tumor stromal area was found to be correlated with diminished metastasis to lymph nodes, as well as reduced tumor budding in the invasive margin and increased tumor-free survival." (PMID 31360118, 2019). "The majority of the CD68+IRF8+ TAMs (78%) were within 20 μm of tumor cells." (PMID 31477692, 2019). "We found CD68-positive cells as well-spread intra-tumoral macrophages and those at the tumor – stroma border, as small round monocytes in mucous tissue, as large phagocytes organized into phagocytic islands, and as macrophages accumulated within adipose tissue." (PMID 31049165, 2019). "Moreover, high numbers of CD68+ M and CD163+ M2 cells within the tumor were significantly associated with worse OS (HR = 1.892, 1.845; p = 0.009, 0.012)." (PMID 31771616, 2019). "However, the CD68+CD206+ TAMs were predominately located within the tumor-nest suggesting that the overall CD206 expression on the CD206+ (CD163−) macrophages (CD68+CD206++ plus CD68+CD206+) decreases as they near the tumor cells." (PMID 31477692, 2019). "Post-treatment CD68 staining correlated positively with baseline SUVmax and post-treatment SUVmax (pre-operative SUVmax), and correlated negatively with the percent of viable tumor cells in the resection specimen." (PMID 30999901, 2019). "However, in patients with tumours poorly infiltrated by CD66b, CD68 and FoxP3, CD20 infiltration did still appear to have a prognostic advantage." (PMID 31882709, 2019). "Interestingly, the high number of CD68++CD163+ TAMs in close proximity to the tumor cell resulted in improved prognosis of patients in our cohort." (PMID 31477692, 2019). "Tumor size in NF-PitNETs is positively correlated with the number of CD68+ macrophages." (PMID 31100921, 2019). "Infiltration of CD68 positive macrophages into tumor tissue was observed in 15 of 42 RCC tissues." (PMID 31905918, 2019). "The tumor displayed immunopositivity for CD68, CD163, and a variable Ki-67 proliferation index." (PMID 31906059, 2019).